MDM2 (MDM2 proto-oncogene)
Diseases named in the same sentence as MDM2 in open-access papers (continued):
Sharing a sentence is not in itself a finding about the gene and the disease.
glioma (continued). "Similar results were seen in LS0082 and SNB19 glioma cells—knocking down ATRX prevented CDK4 inhibitor induced senescence and MDM2 levels did not decrease." (PMID 25803170, 2015). "No other loci, such as MDM2 and CDK4, genes recurrently amplified in gliomas, were amplified in ODA14." (PMID 25378339, 2014). "EGR-1 is commonly suppressed in gliomas in human glioma independent of p16/INK4a/ARF and Mdm2." (PMID 36233659, 2022). "Moreover, OIP5-AS1 expression was downregulated in glioma tissues, and its overexpression enhanced POX but not MDM2 or p21 expression in glioma cells." (PMID 33508123, 2021). "Furthermore, cell death induced by the knockdown of MDM2 was accompanied by the activation of the caspase pathway, as shown by the expression of cleaved caspase-3 and cleaved PARP, which was lower in non-stem glioma cells than in glioma stem cells." (PMID 38612758, 2024).
neuroblastoma (111 papers, 2008 to 2025). Neuroblastoma (NB) is the most common solid, extracranial childhood tumor. "Mechanistic studies using mouse hippocampal cell line HT22 and human neuroblastoma cell line SH-SY5Y revealed a possible association of E3 ligase Mdm2 (double minute 2 protein) with CaV1.2 upon activation of ERα." (PMID 36497108, 2022). "Here, we present the preclinical evaluation of the novel small-molecule MDM2 inhibitor, DS-3032b, for its value for treating patients with high-risk, refractory or relapsed neuroblastoma." (PMID 29416773, 2018). "The pleiotropic activities and low toxicity suggest DS-3032b as the best available candidate to inhibit MDM2 for integration into clinical treatment protocols for high-risk neuroblastoma." (PMID 29416773, 2018). "In this regard, focal amplifications of ALK, CCND1, LIN28B, MDM2, and 19q13.42 observed in our study have been previously implicated in individual neuroblastoma studies 8–12." (PMID 28924153, 2017). "In contrast, Mdm2 deficiency suppressed MYCN driven neuroblastoma tumorigenesis, as evident by an extended tumor latency and survival and reduced tumor incidence and growth in TH-MYCNMdm2 +/− transgenic mice compared with TH-MYCNMdm2 + / + mice." (PMID 23226679, 2012). "A single-nucleotide polymorphism (SNP) in the MDM2 promoter (SNP309T to G) leading to high levels of MDM2 expression has been found in some tumors and is associated with a poor prognostic outcome, including neuroblastoma." (PMID 23226679, 2012). "It has been suggested that the presence of T to G single nucleotide polymorphism (SNP) (SNP309; rs2279744) in the promoter region of MDM2 may increase the MDM2-associated malignant activity and contribute to the development of neuroblastoma." (PMID 33291373, 2020).
neuroblastoma (continued). "In this context, it remains to be shown whether small compounds that selectively inhibit MDM2, such as nutlin-3, and that induce proliferation arrest and apoptosis in neuroblastoma cell lines represent a new therapeutic option for high-risk neuroblastomas." (PMID 18851746, 2008). "For example, in neuroblastoma models, combining MDM2 inhibitors with MYC inhibitors delayed tumor growth and prolonged survival, compared to MDM2 inhibitor monotherapy." (PMID 40002221, 2025). "MYCN and MDM2 inhibition has gained attention not only in neuroblastoma but also in a spectrum of other cancer types due to their potential in targeting key oncogenic pathways." (PMID 39802403, 2025). "An increasing number of targeted agents have entered early pediatric trials, such as HDM-201 (NCT02780128), an MDM2 inhibitor applied to neuroblastoma, and ALRN-6924 (NCT03654716), a dual MDM2/MDMX inhibitor applied to solid tumors in children." (PMID 40115016, 2025). "When MYCN is knocked down, there is a decrease in the sensitivity of MYCN and MDM2 co-amplified neuroblastoma cells to Nutlin-3 and MI-63 treatment." (PMID 39802403, 2025). "Instead, the direct MDM2-MYCN interaction significantly fuels MYCN-amplified neuroblastoma growth and progression." (PMID 39802403, 2025). "In conclusion, the development of effective small molecules that inhibit both MYCN and MDM2 represents a promising new strategy for the treatment of neuroblastoma and other cancers." (PMID 39802403, 2025). "For example, elevated MDM2 expression promotes multidrug resistance in neuroblastoma, leading to relapsed/refractory neuroblastoma." (PMID 40115016, 2025). "In this review, our primary focus will be on the roles of MYCN and MDM2 in the context of neuroblastoma." (PMID 39802403, 2025). "For example, a previous study has reported favorable outcomes of combining 177Lu-octreotate with an MDM2/4 inhibitor in mouse models of neuroblastoma." (PMID 38826727, 2024).
neuroblastoma (continued). "For example, the co-amplification and resulting overexpression of MDM2/CDK4/FRS2 in neuroblastoma patient M787AAA is clinically relevant, and the fusions originating from this amplification are more likely to be passenger events." (PMID 37400763, 2023). "Preclinical studies have demonstrated overexpression of the murine double minute 2 (MDM2) oncogene in some neuroblastoma cell lines." (PMID 37835416, 2023). "In a study on neuroblastoma cell line LA1-55 N, VEGF expression in MDM2 deficient cells lessened considerably resulting in increased sensitivity to the chemotherapy." (PMID 37314603, 2023). "The neuroblastoma patient has a focal amplification in chromosome 12q13-15 involving the oncogenes MDM2 and CDK4 (4–6 copy number log2 fold change, CN l2fc)." (PMID 37400763, 2023). "The MDM2 oncogene is amplified and/or over-expressed in numerous human malignancies, including neuroblastoma, showing poor prognosis in this conditions." (PMID 36139583, 2022). "A previous study proved that Wdr5 regulated the transcription of Mdm2 in neuroblastoma via affecting the level of H3K4me3 at its promoter." (PMID 36358925, 2022). "In this study, we discovered that PF-477736 increased expression of MDM2 oncogene along with CHK1i-induced replication defects in neuroblastoma NB-39-nu cells." (PMID 33014050, 2020). "In neuroblastoma, Mdm2 can acts as a tumor promoting factor as seen in Mdm2 haploinsufficient (Mdm2+/-) MYCN transgenic mice which show a decreased tumor incidence, latency, and reduced tumor growth." (PMID 33585251, 2020). "Other research groups have identified nutlin-3, MI-77301, MI-63, RITA, and RG7112 as MDM2 inhibitors that exhibit anticancer activity in neuroblastoma cells." (PMID 33291373, 2020). "Despite the importance of the MDM2-MYCN axis in neuroblastoma and retinoblastoma, it has been unclear if MDM2 promotes MYCN expression in additional cancers and if MDM2 also regulates MYC." (PMID 33425720, 2020). "Past studies showed that MYCN upregulates MDM2 RNA in neuroblastoma cells by binding to MDM2 promoter E-box sequences, and we here corroborate that ectopic MYCN upregulates MDM2 in MYC-expressing SH-SY5Y." (PMID 33425720, 2020). "Our study focuses on the combined treatment of a MDM2 inhibitor (CGM097) with a BET inhibitor (OTX015) in neuroblastoma." (PMID 33034426, 2020).
neuroblastoma (continued). "Since the majority of neuroblastomas harbor high levels of MDM2, it is critical to develop MDM2 inhibitors for neuroblastoma treatment." (PMID 33291373, 2020). "The mouse double minute 2 (MDM2) homolog gene is amplified and overexpressed in neuroblastoma and contributes to the poor response to treatment and poor prognosis in patients with high-risk neuroblastoma." (PMID 33291373, 2020). "A mass spectrometry analysis of protein binding to MDM2 in the presence of CHK1i identified the centrosome-associated family protein 131 (CEP131), which was correlated with unfavorable prognosis of neuroblastoma patients." (PMID 33014050, 2020). "We revealed that MDM2 was associated with CEP131 protein degradation, whereas overexpression of CEP131 accelerated neuroblastoma cell growth and exhibited resistance to CHK1i-induced replication defects." (PMID 33014050, 2020). "In two neuroblastoma and two retinoblastoma lines, the mechanism involved upregulation of MYCN RNA expression and translation, mediated by MDM2 interaction with the RNA in the neuroblastoma context." (PMID 33425720, 2020). "In this study, we observed that CHK1i induced transient increase of MDM2 protein expression in neuroblastoma cells." (PMID 33014050, 2020). "The authors point out that HDM2 inhibition is especially valuable for the treatment of MYCN-amplified neuroblastoma cell lines, as these cells show remarkable sensitivity to MDM2 antagonists in vitro." (PMID 31331108, 2019). "Within stage 4 neuroblastoma, correlation between MDM2 expression and unfavorable prognosis is limited to MYCN non-amplified tumors, indicating that the correlation is independent of MYCN status." (PMID 29416773, 2018). "MDM2 inhibition has been shown to induce cell cycle arrest, senescence or apoptosis in neuroblastoma cells." (PMID 29416773, 2018). "Aberrant activation of the MDM2 oncogene by gene amplification or inactivation of its inhibitory regulator CDKN2A occurs in 36.6% of primary neuroblastomas." (PMID 29416773, 2018). "Re-analysis of existing expression data from 476 primary neuroblastomas showed that high-level MDM2 expression correlated with poor patient survival." (PMID 29416773, 2018). "Aberrant MDM2 activation has been suggested as a possible mechanism by which neuroblastoma cells escape death." (PMID 29416773, 2018).